PDGFRB (platelet derived growth factor receptor beta)
Diseases named in the same sentence as PDGFRB in open-access papers (continued):
Sharing a sentence is not in itself a finding about the gene and the disease.
cancer (continued). "Furthermore, PDGFRB was consistently found to be within the top 50 hits of each NN ranked list for a total of eight out of the 11 cancer types (with the exceptions being KIRC, LAML and LIHC), with a mean genome-wide rank of 28.5." (PMID 27128408, 2016). "Our analyses also suggest that PDGFRβ may be similarly relevant in additional carcinomas, however, this should be further investigated." (PMID 27128408, 2016). "Note also the very close proximity of PDGFRβ-positive cells to carcinoma cells." (PMID 27128408, 2016). "While analysis the PDGFR specific signatures in MB tumors, we noticed the results from 2 out of 5 data sets showing that PDGFRβ, but not PDGFRα, was associated with miRNA_in_cancer." (PMID 25576913, 2015). "Because the lungs have distinct histologic features, if a cancer cell metastasizes to a small interstitial tissue among the alveoli, it might encounter high interstitial fluid pressure, thereby promoting PDGFRβ expression." (PMID 26163388, 2015). "Expression of PDGFRb on tumor pericytes has allowed targeting of pericytes in cancer therapy, and preclinical analyses have indicated that combined anti-VEGF and anti-PDGF therapy may be beneficial." (PMID 22348394, 2012). "Moreover, Triflorcas hampers survival and anchorage-independent growth of cancer cells characterized by “RTK swapping” by interfering with PDGFRβ phosphorylation." (PMID 23071625, 2012). "The paralog of PDGFRA, PDGFRB, has two alternative promoters and is also a cancer driver gene." (PMID 20208995, 2010). "The pathogenesis of several malignant tumors is associated with overexpression of CSF1R and PDGFRB." (PMID 21171987, 2010). "Notably, this included TGF-β (TGFB1, TGFB3), drivers of adenosine-mediated immune suppression (NT5E (CD73), ENTPD1 (CD39)), Wnt pathway ligands (WNT7A, WNT4), IL10 and drivers/markers of cancer-associated fibroblast activation (INHBA, WNT7A, TGFB1, FAP, PDGFRA, PDGFRB)." (PMID 39568014, 2024). "PDGFRB may be a prime candidate for disease modulation and is listed as a targetable gene (via Cediranib, Masitinib, Pazopanib) from the Genomics of Drug Sensitivity in Cancer." (PMID 37200395, 2023). "Additionally, we measured mRNA levels of the cancer-associated fibroblast-related genes described in the literature such as αSMA, or that resulted from IPA analysis including SDF1, TGF-β, PDGFRβ, and FAP in an independent cohort of PCAFs, PNAFs, and BHPFs derived from patients." (PMID 35740605, 2022). "The fibroblasts encompassed 4 major populations defined by key cancer-associated fibroblast (CAF) markers, including fibroblast activation protein (FAP), alpha smooth muscle actin (αSMA, ACTA2), podoplanin (PDPN), and platelet-derived growth factor receptor beta (PDGFRβ)." (PMID 34385456, 2021). "Activation of PDGFRb, in particular on fibroblasts, has also been demonstrated to induce an upregulation of hepatocyte growth factor (HGF) and stanniocalcin-1 (STC1), with the latter having furthermore been linked to increased distant metastasis in several murine cancer models." (PMID 33661437, 2021). "Notably, bone marrow stromal cells highly express PDGFRβ, while minimally detected in cancer cells." (PMID 29455663, 2018). "The overexpression of PDGFRβ could be a biomarker for cancer diagnosis." (PMID 29991770, 2018). "We aimed to ascertain whether PDGFRB is a MPM-cancer driver gene." (PMID 28435517, 2017). "Overall, our data suggest that PDGFRβ can serve as a reliable marker for identification of CAFs in OSCC, and offer a list of additional candidates that may serve as an important resource for CAF detection and diagnostic strategy development in cancers." (PMID 27128408, 2016).
cancer (continued). "It is important to note that in our study PDGFRβ was not expressed on carcinoma cells, however with the limited number of specimens analyzed, we cannot exclude a possibility that PDGFRβ may be expressed in a subset of OSCCs, as has been shown for other cancers." (PMID 27128408, 2016). "It has been demonstrated that EGFRvIII-dependent cancers may escape targeted therapy by developing dependence on PDGFRβ signaling, thus providing a strong rationale for combination therapy aimed at blocking both EGFRvIII and PDGFRβ signaling." (PMID 26461476, 2015). "In this study, we sought to screen potential biomarkers for NMIBC diagnosis and prognosis by constructing a cancer-associated PPI network based on the healthy human urinary proteome, and we revealed that PDGFRB could serve as a prognostic biomarker for NMIBC recurrence." (PMID 24801713, 2014). "Furthermore, evidence exists to suggest that a functional relationship between P-Rex1 and PDGFRβ as described here may be a contributing factor to cancer progression in vivo." (PMID 23382862, 2013). "Strikingly, Dkk3‐null cancer cells led to an increase in myCAF gene expression (ACTA2, CTGF, PDGFRB), with concomitant downregulation of inflammatory CAF markers (CXCL12, CXCL2) in PSCs." (PMID 41147409, 2026). "CAFs educated by shSMYD3 or shCDCP1 cancer cells displayed a marked reduction in protein levels of α-SMA, FAP, PDGFRβ and S100A4 compared with shNC controls (densitometry, mean ± SEM; p < 0.001)." (PMID 41301830, 2025). "The pathway enrichment analysis showed that PDGFRB and PDGFRA were involved in Reactome pathway R‐HSA‐2219528 (PI3K/AKT Signaling in Cancer), which was overrepresented in DEGs found in the α‐SMA+ stroma of G2 and G3 tumors." (PMID 39245631, 2025). "For many targets like CLMP, PDGFRB, NOTCH2, and GPC6, TCGA SARC samples had the highest median expression compared with other cancer types in the TCGA Pan-Cancer Atlas." (PMID 40814001, 2025). "Conditioned by CDCP1-high SW480 or HCT116 cells, CAFs displayed a protumor phenotype with upregulation of α-SMA, FAP, PDGFRβ, and S100A4, indicating that cancer-cell CDCP1 promotes fibroblast activation." (PMID 41301830, 2025). "We observed differential expression of four genes, ALB, KIT, PDGFRB, and TGFBR1, in regular and neighbouring cancer tissues." (PMID 39364054, 2024). "These included, but were not limited to: PECAM1 and CDH5 (EC markers), PDGFRA (fibroblast marker), PDGFRB (pericyte marker), and EPCAM and KRT18 (cancer cell markers)." (PMID 38183074, 2024). "Within this set of genes, a subset, notably CSF2RA, CRLF2, IL1R1, IL7R, and PDGFRB, exhibited intricate connections with the JAK-STAT pathway, which is crucial for the viability of cancer cells." (PMID 38743676, 2024). "Further studies have identified a link between PDGFRβ expression in TNBC, and cancer stem cells, where FOXC2 induces cancer stem cell characteristics and metastasis by upregulating PDGFRβ expression." (PMID 38699644, 2024). "PDGFRA and PDGFRB have 0.49 and 0.53 of the correlation coefficiency for ERG expression, respectively, in S:E fusion-positive cancer." (PMID 36579559, 2022). "Most cancers presented PDGFRA, PDGFRB, PDPN, ACTA2, and FAP hypermethylation compared to normal samples." (PMID 36032075, 2022). "Taking together, our results suggest that HOTAIR is able to regulate the proliferation of cancer cells by modulating YBX1 nuclear localization, promoting in turn PCK2 and PDGFRB expression." (PMID 34266873, 2021). "The scaffolding protein EBP50 also is involved in the pathogenesis of cancer by interacting with EGFR and PDGFRβ with its PDZ domains." (PMID 32708604, 2020). "As expected, CAFs expressed PDGFRβ and FSP1, and cancer cells E‐cadherin and PAX8, whereas both cell types were positive for vimentin and N‐cadherin." (PMID 32115889, 2020). "There were some RTK genes (EPHB6, EPHA1, EPHB3, FGFR4, PDGFRB, and FLT4) showing amplification in cancer cells." (PMID 32038722, 2019).
cancer (continued). "PDGFRα and PDGFRβ have been shown to play a critical role in Foxq1-mediated epithelial–mesenchymal transition (EMT) and regulate cancer stemness and chemoresistance." (PMID 30777101, 2019). "Therefore, the addition of a PDGFRβ inhibitor to existing targeted agents could potentially aid in obtaining a durable response in the clinic and should be considered in future clinical trial evaluations of combination-targeted therapy across multiple cancers." (PMID 30777101, 2019). "With the aim of evaluating the effects of cancer cells upon the hASCs' capability of promoting angiogenesis, CD31, VEGF, PDGFA, PDGFRα, PDGFRβ gene expression was analysed at 7, 14 and 21 days." (PMID 28102844, 2017). "Of note, the overlap between the top 50 genes of the five most closely related cancer types (OSCC, LUAD, LUSC, BLCA and PAAD), yielded a set of 11 genes that included PDGFRB." (PMID 27128408, 2016). "This is further supported by other genes that correlated closely in many cancer forms such as FAP, PDGFRB, THBS2 and VCAN which are also markers for matrix-producing cells and in some cases also for cancer-associated fibroblasts." (PMID 27809802, 2016). "Given that c-MYC is a well-known driver of oncogenesis in many models and cancer types, and that JAG2 is a c-MYC-regulated gene, the PDGFRβ-c-MYC-JAG2 pathways would be a logical and expected mechanism of MB carcinogenesis." (PMID 25576913, 2015). "We have examined the effect of CCL5- or CCR5-blockers administered as single agents or in combination with a murine PDGFRβ-directed treatment, this strategy being currently under clinical evaluation for the treatment of CRC cancers." (PMID 22205974, 2011). "TCPTP is a well-characterized negative regulator of several cancer relevant RTKs including EGFR, cMet, PDGFRβ, Insulin receptor, and VEGFR2." (PMID 20055993, 2010). "This compound attenuates PDGFRβ and VEGFR2 signalling in cells in a TCPTP-dependent manner and functions as a negative regulator of EGFR phosphorylation in cancer cells." (PMID 20055993, 2010). "Furthermore, PDGFRB is involved in key signaling pathways, including the MAPK and PI3K/AKT pathways, which are crucial for cancer cell survival and migration." (PMID 41376620, 2025). "Importantly, both PDGFRB and FGFR4 have been investigated as potential therapeutic targets for cancer treatments, providing possible alternative avenues for targeted treatment in patients with these alterations." (PMID 41509216, 2025). "Aortic carboxypeptidase-like protein (ACLP) activates the CAF markers such as actin alpha 2 (ACTA2), FAP, and platelet-derived growth factor receptor beta (PDGFRB) via TGF-β1 signaling, enhancing cancer cell migration and reducing CD8+ T cell infiltration, thereby creating an immunosuppressive TME." (PMID 40486875, 2025). "VEGFA, PDGFRB, ANGPTL4 and ENG have been shown to play major roles in angiogenesis and vascular homeostasis, not only in physiological regeneration but also in most pathological angiogenic processes such as cancer." (PMID 38882056, 2024). "Ampelopsin exerts its anti-cancer ability through the regulation of growth factor receptor (VEGFR2 and PDGFRβ) and TRAIL/TRAIL-R pathways; moreover, its anti-inflammatory ability is exerted through the modulation of the toll-like receptor 4 (TLR4) pathway or binding to the ryanodine receptor." (PMID 35624699, 2022). "However, the expression of the PDGFRA, PDGFRB, CDH11, and EMILIN1 genes was mainly reduced in fibroblasts after co-cultivation with cancer cells." (PMID 36263012, 2022). "However, none of these markers are specific for myofibroblasts: FSP1 is also expressed in macrophages and cancer cells, FAP is expressed in some immune cells, and desmin and PDGFRβ are in perivascular cells." (PMID 36542704, 2022).
cancer (continued). "Human triple-negative breast and ovarian cancer studies have yielded 3–4 CAF subtypes, designated CAF S1–S4 based on the differential expression of six fibroblast markers (FAP, integrin β1/CD29, α-SMA, S100-A4/FSP1, PDGFRβ, and caveolin-1)." (PMID 36010899, 2022). "AR, IGF1R, PDGFRB, PIK3R1, and SUFU involved in KEGG pathways in cancer." (PMID 34208639, 2021). "Several cancer-relevant genes, including cyclin A, telomerase reverse transcriptase (TERT), platelet-derived growth factor receptor beta (PDGFRB), and mitogen-activated protein kinase 1 (MAPK1), change their expression following the integration of HBV into host DNA." (PMID 34440678, 2021). "Thus, we analyzed the impact of PDGFRB gene silencing on MPM cell proliferation, cell cycle, apoptosis induction, and invasive behavior on a panel of cell lines, in order to widen the cancer representativeness." (PMID 28435517, 2017). "Overall, this study identified PDGFRβ as a novel marker of stromal activation in OSCC, and further characterized a list of promising candidate CAF markers that may be relevant to other carcinomas." (PMID 27128408, 2016). "Sorafenib is a multikinase inhibitor of Raf kinase, which is involved in cancer cell proliferation, and also of vascular endothelial growth factor receptor-2/-3 (VEGFR-2/-3) and platelet-derived growth factor receptor-beta (PDGFR-β), which are involved in peritumor neovascularization." (PMID 28943630, 2015). "Because many receptor proteins (e.g., EGFR, PDGFRA, PDGFRB, ERBB2, and ERBB4) are typically located in the upstream of cancer-related signaling pathways such as proliferation, cell death, and cell cycle progression, mutations in these genes are likely critical to cancer development." (PMID 24516372, 2014). "MEDI-575 is a human mAb that selectively binds to PDGFRα with high affinity, inhibiting signaling from PDGFRα on cancer cells and supportive stroma without inhibiting PDGFRβ." (PMID 25149088, 2014). "As the gene-drug target interactions are not specific for a certain cancer type, these results might suggest a potential dual role of PDGFRB." (PMID 40258059, 2025). "Indeed, although PDGFRB mutations are not often mentioned, EGFR and ERBB2 are involved in cancer research and targeted treatment." (PMID 39678505, 2024). "As the FGF2 rs1048201, PDGFRB rs246395, PDGFRA rs2228230, MMP2 rs243865, rs7201, and TIMP2 rs7501477 have not been previously examined in HNSCC in terms of survival and treatment outcome, this is most likely the first report describing their prognostic and predictive value in this type of cancer." (PMID 35406617, 2022). "Furthermore, Girdin impaired Platelet Derived Growth Factor Receptor Beta (PDGFRβ) degradation, which in turn, promoted PKM2 tyrosine residue 105 (Y105) phosphorylation and inhibited PKM2 activity, subsequently promoting aerobic glycolysis in cancer cells." (PMID 36428781, 2022). "In line with the oncogenic role of these genes, we observed a decrease in proliferation of H226 cells when either PDGFRB or COL1A1 were inhibited, additive to the effect achieved with GAS6 downregulation alone, supporting the existence of a SWINGN-dependent oncogenic hub in this cancer type." (PMID 32071317, 2020). "However, our finding that selective targeting of PDGFRβ in cancer models with high PDGF-BB expression did have a therapeutic effect, suggests that specific PDGFRβ kinase inhibitors may have a value in cancer therapy." (PMID 31938055, 2020). "Our data thus suggests that even though dual combination of MEK-JAK inhibition showed some degree of growth suppression, it does not impact on cancer stem cell contents; however, additional suppression of PDGFRβ is able to dramatically reduce this subpopulation." (PMID 30777101, 2019). "However, a pan-cancer analysis of PDGFRB has not yet been carried out." (PMID 40128057, 2025).
cancer (continued). "Moreover, the immunofluorescent assays showed that FAM-labeled ZTRI was greatly accumulated in carcinoma specimen and co-localized well with PDGFRβ in HCC tissues, suggesting that ZTRI-based tracer might be developed for detection of PDGFRβ overexpressed in HCC." (PMID 37256321, 2023). "This study revealed diverse possible candidate mechanisms by which imatinib resistance to PDGFRB inhibition may arise in DFSP, and highlights the usefulness of whole-genome sequencing in identifying drug resistance mechanisms and in pursuing genome-directed, personalized anti-cancer therapy." (PMID 23922791, 2013). "We also noted a change in the expression level of 3 genes (PDGFRB, EMILIN1 and ASPN) during cultivation of the primary cell line of skin fibroblasts in the absence of cancer cells for 4 weeks." (PMID 36263012, 2022). "We also noted high baseline expression of several other potential therapeutic targets including VEGFB, TGFB3, PDGFB/PDGFRB, FGFR1 and IGF1R in cancers that did not achieve pCR." (PMID 30967156, 2019). "For instance, we found that, while many proteins belong to the druggable categories, including several “star” molecules including PDGFRB, CDK4, and PI3KCA derived from cancer driver gene analyses, their elevated expressions are not correlated with poor survival." (PMID 29520031, 2018). "Staining for PDGFRβ was significantly more intense in CAS compared to normal stroma, and no staining could be detected in epithelial cancer cells." (PMID 28531107, 2017).